PYCR1 (pyrroline-5-carboxylate reductase 1)
Diseases named in the same sentence as PYCR1 in open-access papers (continued):
Sharing a sentence is not in itself a finding about the gene and the disease.
ampullary cancers (1 paper, 2016). "This 3-gene expression model suggests that the collective expression of IRX3, PYCR1, and TMPRSS3 reflects the additional biological importance of tumor invasion, intestinal differentiation, and cellular metabolism, in the prognosis of ampullary cancers." (PMID 27549176, 2016).
asthma (1 paper, 2023). "To explore the alterations in proline and PYCR1 and the underlying mechanisms in asthma, we developed a murine model of chronic asthma." (PMID 37432745, 2023). "To further elucidate the roles of Pycr1 in airway remodeling in asthma, we generated Pycr1 gene–deficient mice by using the CRISPR/Cas9 method." (PMID 37432745, 2023). "Consistently, we observed that loss of Pycr1 mitigated subepithelial collagen deposition around airways, rescued the expression of E-cadherin in airway epithelial cells, and reduced the production of collagen type I in the lung tissue of the asthma model." (PMID 37432745, 2023). "The mRNA transcript level of the Pycr1 gene was upregulated in lung homogenates of an HDM-induced asthma model for 14 days; however, the association of the expression of the PYCR1 protein with airway remodeling remains unclear." (PMID 37432745, 2023). "PAS staining revealed that the asthma model in Pycr1-KO mice exhibited a decreased tendency of mucus secretion compared with that in WT mice." (PMID 37432745, 2023). "In the present study, increased levels of plasma proline and PYCR1 were observed in patients with asthma." (PMID 37432745, 2023). "In line with the increased proline, PYCR1 was significantly elevated in patients with asthma compared with the control group." (PMID 37432745, 2023). "Then, WT mice and Pycr1-KO mice were subjected to PBS or HDM to induce the experimental asthma model." (PMID 37432745, 2023). "Collectively, these results suggested that Pycr1 was involved in the regulation of inflammation and EMT-associated airway remodeling in the HDM-driven asthma model." (PMID 37432745, 2023). "In summary, our study demonstrates that proline metabolism, especially PYCR1, plays a vital role in asthma." (PMID 37432745, 2023). "Amino acids and related enzymes in the arginine and proline pathways, especially proline and PYCR1, were distinctively altered in patients with asthma compared with controls." (PMID 37432745, 2023). "Conversely, the degree of inflammation was lower in the asthma model of Pycr1-KO mice than in WT mice." (PMID 37432745, 2023). "We propose that agents that selectively target PYCR1 activity and block the source of proline would likely be an efficacious therapy for asthma treatment." (PMID 37432745, 2023). "In this study, we demonstrate that proline and PYCR1 are elevated in plasma in patients with asthma compared with healthy controls." (PMID 37432745, 2023). "A previous study indicated that the mRNA level of Pycr1 was upregulated in the airway epithelium of an HDM-induced asthma model." (PMID 37432745, 2023). "To investigate the effect of proline metabolism on HDM-induced airway remodeling, we adopted 3 methods in a murine asthma model, including inhibition of PYCR1, a proline-free diet (PFD), and combined therapy." (PMID 37432745, 2023). "In the HDM-induced asthma model characterized by airway inflammation and remodeling, proline and PYCR1 were increased." (PMID 37432745, 2023). "Since epithelial cells initialize EMT, we next assessed PYCR1 mRNA expression in the airway epithelium between patients with asthma and healthy controls." (PMID 37432745, 2023). "Inhibition of PYCR1 or reduction of proline relieved airway remodeling in asthma." (PMID 37432745, 2023). "For this reason, and because PYCR1 protein is located in mitochondria and PYCR1 mRNA is higher in bronchial cells from patients with asthma, we hypothesized that PYCR1 might influence the biology of epithelial cells and mitochondria." (PMID 37432745, 2023). "Collectively, proline and PYCR1 in plasma from patients with asthma were significantly increased, so they may be involved in asthma pathogenesis." (PMID 37432745, 2023). "Moreover, receiver operating characteristic (ROC) curve analysis was performed to evaluate the potential of proline and PYCR1 as biomarkers for asthma." (PMID 37432745, 2023). "PYCR1 gene expression is upregulated in bronchial epithelial cells in asthma." (PMID 37432745, 2023).
asthma (continued). "Given that restraint of EMT is seen in PYCR1-inhibited or proline-free diet mice, PYCR1 and proline may be potential drug targets for airway remodeling therapy in asthma." (PMID 37432745, 2023). "Plasma proline and PYCR1 are increased in patients with asthma." (PMID 37432745, 2023). "Overall, PYCR1 mRNA expression was upregulated in the epithelial cells of patients with asthma and correlated with the severity of the disease, which may be associated with epithelial cell status changes." (PMID 37432745, 2023). "However, the relationship between proline/PYCR1 and the clinical features of asthma remains unsolved." (PMID 37432745, 2023). "Therefore, the elevation of proline and PYCR1 in bronchial epithelial airways in asthma may be involved in the pathogenesis of asthma." (PMID 37432745, 2023). "Collectively, proline and Pycr1 could be involved in EMT-mediated airway remodeling in asthma." (PMID 37432745, 2023). "In addition, deprivation of exogenous proline or inhibition of PYCR1 activity could suppress key asthma features, especially EMT-mediated remodeling." (PMID 37432745, 2023). "This led us to explore whether PYCR1 and proline affect airway remodeling in an HDM-driven model of asthma." (PMID 37432745, 2023). "Together, these results demonstrated that restriction of endogenous proline by inhibition of PYCR1 and reduction of exogenous proline via a PFD, to some extent, attenuate inflammation and airway remodeling in a murine asthma model induced by chronic HDM exposure." (PMID 37432745, 2023). "PYCR1 was dominantly located in mitochondria and played an important role in metabolism; hence, it is natural to investigate whether mitochondrial changes or cellular metabolic process alterations existed in the HDM-driven asthma model." (PMID 37432745, 2023). "However, there is a lack of detailed information on whether and how PYCR1 regulates EMT-mediated airway remodeling through proline production in asthma." (PMID 37432745, 2023).
autosomal recessive cutis laxa type 2 (1 paper, 2021). A spectrum of connective tissue disorders characterized by the association of wrinkled, redundant and sagging inelastic skin with growth and developmental delay, and skeletal anomalies. "Indeed, PYCR1 mutation has been described in patients with multisystem disorders such as autosomal-recessive cutis laxa type 2 (ARCL2) characterized by premature aging, general developmental delay, and skin and joint laxity." (PMID 34277596, 2021).
Burkitt lymphoma (1 paper, 2021). A rare form of malignant mature B-cell non-Hodgkin lymphoma. "In Burkitt lymphoma, MYC suppressed POX/PRODH expression and increased P5CS and PYCR1, leading to reprogramming of proline and glutamine metabolism." (PMID 33465163, 2021).
chronic asthma (1 paper, 2023). An asthma that is characterized by the development of persistent airway inflammation and recurrent attacks of breathlessness and wheezing, which vary in severity and frequency. "Additionally, we found that Pycr1 deficiency reduced airway hyperresponsiveness compared with WT mice in the chronic asthma model." (PMID 37432745, 2023). "We also assessed whether Pycr1 affects proline metabolism in the context of a chronic asthma model, demonstrating that Pycr1 deficiency reduced the level of proline in the lungs of HDM-challenged mice." (PMID 37432745, 2023). "According to these strategies, we first evaluated whether the inhibition of endogenous proline synthesis via the inhibition of PYCR1 could block EMT-associated airway remodeling in a chronic asthma model." (PMID 37432745, 2023). "Knockout of Pycr1 attenuated airway remodeling in an HDM-induced chronic asthma model." (PMID 37432745, 2023).
de Barsy syndrome (1 paper, 2023). "Like for other progeroid conditions such as PYCR1 inactivation in De Barsy syndrome, this RAF1 loss‐of‐function phenotype provides another illustration of how genes that are hijacked in the context of cancer may inversely cause premature aging when inactivated." (PMID 37066513, 2023).
epilepsy (1 paper, 2019). A brain disorder characterized by episodes of abnormally increased neuronal discharge resulting in transient episodes of sensory or motor neurological dysfunction, or psychic dysfunction. "In addition to intrauterine growth retardation and skeletal abnormality (hip dislocation), mutated PYCR1 in human patients caused abnormalities in the central nervous system, such as mental retardation, microcephaly, corpus callosum agenesis, and epilepsy." (PMID 31091804, 2019).
head and neck squamous cell carcinoma (1 paper, 2024). A squamous cell carcinoma that arises from any of the following anatomic sites: lip and oral cavity, nasal cavity, paranasal sinuses, pharynx, larynx, and salivary glands. "PYCR1 mRNA was highly expressed in SNSCC compared with NP tissues, consistent with the findings in the TCGA with head and neck squamous cell carcinoma database." (PMID 39768999, 2024).
Hernia (1 paper, 2018). "Moreover, a candidate gene study for scrotal hernia in pigs obtained a highly significant association between PYCR1 and hernia." (PMID 29843603, 2018).
keloid (1 paper, 2023). An irregularly shaped, elevated mark on the skin caused by deposits of excessive amounts of collagen during wound healing. "We observed that human fibrotic tissues (hypertrophic scar and keloid) have higher expression of Arg1, OAT and PYCR1 than normal skin." (PMID 37752116, 2023).
lentivirus infection (1 paper, 2022). Virus diseases caused by the Lentivirus genus. "Then the level of mRNA and protein was assayed for PYCR1 using RT-qPCR and Western blot 3 days after the lentivirus infection." (PMID 35371311, 2022).
leukodystrophy-hypomyelinating 10 (1 paper, 2021). "Genetic defects in PYCR2, a PYCR1 paralog, are associated with leukodystrophy-hypomyelinating 10 (HLD10), a syndrome characterized by microcephaly and psychomotor disability." (PMID 34458276, 2021).
metastatic tumors (1 paper, 2007). "The highest PYCR1 expression in our PCa samples was found in biopsies from metastatic tumors, possibly as a result of atypical AR activation." (PMID 17553165, 2007).
nasopharyngeal carcinoma (1 paper, 2021). A carcinoma arising from the nasopharyngeal epithelium. "This provides a new perspective of nasopharyngeal cancer involving both hsa-miR-150-5p and PYCR1 for the treatment of nasopharyngeal cancer." (PMID 34696668, 2021). "The expression levels of hsa-miR-150-5p was reduced in the nasopharyngeal cancer tissues and cells and were negatively correlated with the PYCR1 levels." (PMID 34696668, 2021). "The overexpression of hsa-miR-150-5p and PYCR1 was detected by cell viability, proliferation, western blotting, migration, and invasion in nasopharyngeal cancer cells." (PMID 34696668, 2021). "However, the molecular mechanism of the hsa-miR-150-5p-PYCR1 axis in nasopharyngeal cancer remains unclear." (PMID 34696668, 2021). "Nonetheless, the functions of PYCR1 in nasopharyngeal cancer have not been studied." (PMID 34696668, 2021).
neurocutaneous syndrome (1 paper, 2018). A group of disorders characterized by ectodermal-based malformations and neoplastic growths in the skin, nervous system, and other organs. "This study also provided a comprehensive linkage of extracellular space genes for the neurocutaneous syndrome caused by PYCR1 mutations." (PMID 30574417, 2018). "In this study, we provided the first characterization of the transcriptome for PYCR1 mutations causing the neurocutaneous syndrome ARCL2B." (PMID 30574417, 2018).
oligodendroglioma (1 paper, 2024). A well-differentiated (WHO grade II), diffusely infiltrating neuroglial tumor, typically located in the cerebral hemispheres. "As a control, oligodendroglioma cultures without the IDH mutation were used, in which PYCR1 activity was less pronounced." (PMID 38275897, 2024).
osteoarthritis (1 paper, 2021). A noninflammatory degenerative joint disease occurring chiefly in older persons, characterized by degeneration of the articular cartilage, hypertrophy of bone at the margins and changes in the synovial membrane. "In two in vitro chondrocyte models that reproduce the main features of osteoarthritis (OA) chondrocytes including a downregulation of chondrocyte markers, a significant decrease of PYCR1 was observed." (PMID 34277596, 2021).
ovarian carcinoma (1 paper, 2024). A malignant neoplasm originating from the surface ovarian epithelium. "Progression-free survival depended on the expression level of MMP12, MMP13, PYCR1 and GPx1 in patients with ovarian cancer." (PMID 38397798, 2024). "Secondly, the risk of ovarian cancer increased with age in association with MMP3, MMP10, MMP7, TIMP3, POX/PRODH, PYCR1, PYCR3 to indicate degenerative histological changes." (PMID 38397798, 2024).
ovarian neoplasm (1 paper, 2024). A benign, borderline, or malignant neoplasm involving the ovary. "The conversion of glutamine to proline seems to be involved in OC progression since PYCR1 and PYCR3 expression was higher in ovarian neoplasm samples from FIGO III/IV stages as compared to the control group." (PMID 38397798, 2024).
proline metabolic disorder (1 paper, 2019). "Patients carrying PYCR1 gene deficiency showed proline metabolic disorder, which leads to premature aging phenotypes, intrauterine growth retardation, triangular facial gestalt, psychomotor retardation, hypotonia, and ophthalmologic abnormalities, and progeroid cutaneous manifestations." (PMID 31091804, 2019).
schizophrenia (1 paper, 2024). A major psychotic disorder characterized by abnormalities in the perception or expression of reality. "In contrast, the level of the proline synthesis enzyme PYCR1 was higher in schizophrenia patients, although two other proline synthesis enzymes, ALDH18A1 and PYCR2, exhibited slightly lower levels compared to healthy controls." (PMID 37815900, 2024).
skin aging (1 paper, 2018). The gradual irreversible changes in structure of skin that occur as a result of the passage of time.. "POSTN has never been described in PYCR1-related ARCL, and our results indicate that POSTN may play an important role in skin aging, heart valves disease, and preglaucoma." (PMID 30574417, 2018).
Umbilical hernia (1 paper, 2018). Protrusion of abdominal contents through a defect in the abdominal wall musculature around the umbilicus. "None of the polymorphisms detected in the four candidate genes outside the QTL-region on SSC14 (VCAN, MMP13, PYCR1 and VIM) obtained significant associations with umbilical hernia." (PMID 29843603, 2018).
wrinkly skin syndrome (1 paper, 2017). "Biallelic PYCR1 mutations were identified in patients previously diagnosed with GO, wrinkly skin syndrome, or ARCL2, but these mutations are now classified as ARCL2B." (PMID 28294978, 2017).
tumor (90 papers, 2012 to 2026). "In fact, increased expression of PYCR1 is associated with many human cancers, while knockdown of PYCR1 in cancer cells transplanted into mice markedly decreased tumor growth." (PMID 40454316, 2025). "Decreasing proline synthesis by reducing the level of pyrroline-5-carboxylate reductase 1 (PYCR1) in cancer-associated fibroblasts is sufficient to reduce tumor collagen production, tumor growth, and metastatic spread in vivo." (PMID 38921453, 2024). "Higher PYCR1 expression was associated with various clinicopathological features, such as metastasis and advanced tumor stage." (PMID 39768999, 2024). "Specifically, we observed for the first time that PYCR1, a gene involved in proline metabolism, exhibits promise as a tumor-associated marker and can be significantly used as a prognostic biomarker in SNSCC." (PMID 39768999, 2024). "The results showed that tumor formation rates of PYCR1-deficient group were significantly decreased." (PMID 37845207, 2023). "Cancer-associated fibroblasts increase in PYCR1 expression and proline synthesis for collagen production, highlighting the importance of proline in the establishment of a tumor-supportive environment." (PMID 37672588, 2023). "More intriguingly, the tumor growth inhibited by PYCR1-deficiency in immunocompetent mice was superior to that in immunodeficient mice." (PMID 37845207, 2023). "Clinically, the high ASS1/PYCR1 expression was associated with the tumour stage, even in EOC compared to normal tissue samples, and the progression-free survival of OSCC patients." (PMID 36978187, 2023). "In 3D culture, which is more representative of the oxygen and nutrient gradients observed in the tumor microenvironment, we also found that PYCR1 loss reduced proline export." (PMID 35108535, 2022). "Loss of PYCR1 in cells results in significant metabolic rewiring, and loss of PYCR1 in tumors results in cell death and reduced tumor growth." (PMID 35108535, 2022). "Loss of PYCR1 in vivo results in an unsustainable compensatory increase in respiration, cell death, and decreased tumor growth." (PMID 35108535, 2022). "Consequently, this finding shows that high expression of PYCR1 can be used as a tumor-associated biomarker to predict the prognosis of SNSCC." (PMID 39768999, 2024). "PYCR1 was validated as a significant SNSCC marker through RT-qPCR, and its high expression correlated with poor overall patient survival, suggesting PYCR1 could serve as a tumor-associated prognostic biomarker for SNSCC." (PMID 39768999, 2024). "Furthermore, intraperitoneal injections of proline into tumor-bearing mice rescued PYCR1 deficiency-induced decreased levels of cGMP and cGMP-PKG signaling related components in xenograft tumors." (PMID 37845207, 2023). "Thus, our study implies that targeting PYCR1 may also offer opportunities to tackle tumour-associated fibrosis to improve effective drug delivery and immune cell recruitment." (PMID 35760868, 2022). "Pyrroline-5-carboxylate reductase 1 (PYCR1) is a key enzyme in the proline biosynthesis pathway and has garnered widespread attention in the field of tumor research in recent years." (PMID 41975648, 2026). "The tumor size was significantly reduced in NSG mice xenografted with PYCR1-KO A549 cells compared with those xenografted with Ctrl A549 cells." (PMID 41254241, 2025). "c‐Myc, a well‐characterized oncogenic transcription factor, directly upregulates PYCR1 expression, thereby linking proline metabolism to tumor growth." (PMID 41200384, 2025). "Further investigation using a 3D tumor spheroid formation assay revealed significantly smaller tumor spheroids in PYCR1-KO A549 and PYCR1-KO H1299 cells compared with control cells." (PMID 41254241, 2025). "Combination therapy of the PYCR1 inhibitor pargyline and bortezomib reduced tumour load in a 3D model and reduced serum activin A levels in 5TGM1-bearing mice." (PMID 40932053, 2025).